ATP2B1 (ATPase plasma membrane Ca2+ transporting 1)
Diseases named in the same sentence as ATP2B1 in open-access papers (continued):
Sharing a sentence is not in itself a finding about the gene and the disease.
colon cancer (3 papers, 2017 to 2023). "Compared to normal human colonic cells (NCM460), the expression of ATP2B1.AS1 and NSMCE1.DT were higher in colonic cancer cells (including HCT116 and LoVo), while AC007728.3 exhibited a contrasting trend." (PMID 37629096, 2023). "Among them, AP003555.1, ATP2B1.AS1, and NSMCE1.DT have been shown in previous studies to be closely related to colon cancer prognosis." (PMID 37629096, 2023). "Specifically, ATP2B1.AS1 and NSMCE1.DT exhibited higher expression in colon cancer tissues compared to noncancerous tissue, as well as higher expression in colonic cancer cell lines than in human normal cell lines." (PMID 37629096, 2023). "To further confirm the accuracy of the signature in predicting patient prognosis, we used the Kaplan–Meier plotter database to examine the predictive significance of ATP2B1.AS1 and NSMCE1.DT in colon cancer, while AP003555.1 and AC007728.3 were absent in the database." (PMID 37629096, 2023).
ovarian carcinoma (3 papers, 2020 to 2022). A malignant neoplasm originating from the surface ovarian epithelium. "In this study, we also showed that parent genes such as BCLAF1, FBLN1, ARHGAP23, STON2, UBQLN4, and ATP2B1 were significantly positively correlated with the survival rate of patients with ovarian cancer." (PMID 35978436, 2022). "We found that the expression of six genes (BCLAF1, FBLN1, ARHGAP23, STON2, UBQLN4, and ATP2B1) had a significant positive correlation with the survival rate of patients with ovarian cancer." (PMID 35978436, 2022).
developmental delay (2 papers, 2024 to 2026). "This study aimed to identify the genetic etiology in a Chinese infant with a neurodevelopmental disorder characterized by early-onset seizures and global developmental delay (GDD) and functionally characterize a novel ATP2B1 missense variant." (PMID 41853798, 2026).
gastric cancer (2 papers, 2016 to 2021). A primary or metastatic malignant neoplasm involving the stomach. "Our data showed that circRNA circATP2B1 (also called hsa_circ_000826) was overexpressed in gastric cancer tissues instead of linear ATP2B1 mRNA, and it promoted aerobic glycolysis in gastric cancer cells." (PMID 33996547, 2021).
Sepsis (2 papers, 2023 to 2025). Sepsis is defined as life-threatening organ dysfunction caused by a dysregulated host response to infection. "ATP2B1.AS1 is strongly associated with cell inflammation and can regulate the miR-23a-3p/TLR4 axis, exacerbating sepsis-induced cell apoptosis and inflammation." (PMID 37629096, 2023).
atrial fibrillation (1 paper, 2022). A disorder characterized by an electrocardiographic finding of a supraventricular arrhythmia characterized by the replacement of consistent P waves by rapid oscillations or fibrillatory waves that vary in size, shape and timing and are accompanied by an irregular ventricular response. "The variant in ATP2B1 gene (rs2681492) was associated with CAD and rs2810915 variant in PTCH1 gene was significantly associated with atrial fibrillation." (PMID 36407428, 2022).
autosomal dominant intellectual developmental disorder 66 (1 paper, 2026). "Heterozygous pathogenic variants in ATP2B1 (encoding PMCA1) cause autosomal dominant intellectual developmental disorder 66 (MRD66; OMIM #619910)." (PMID 41853798, 2026).
cerebellar ataxia (1 paper, 2022). A neurological syndrome characterized by clumsy and uncoordinated movement of the limbs, trunk, and cranial muscles. "In humans, genetic mutations in ATP2B1, ATP2B2 and ATP2B3 gene have been linked with hearing loss, cerebellar ataxia and global neurodevelopmental delay: all of them were found to impair pump activity." (PMID 36207321, 2022).
cholangiocarcinoma (1 paper, 2022). A carcinoma that arises from the intrahepatic biliary tree (intrahepatic cholangiocarcinoma) or from the junction, or adjacent to the junction, of the right and left hepatic ducts (hilar cholangiocarcinoma). "The results showed that ATPase plasma membrane Ca2+ transporting-1 (ATP2B1 or PMCA1) plays an important role in the prognosis of cholangiocarcinoma." (PMID 35875160, 2022). "The results showed that the levels of CD4+ and CD8+ T cells in cholangiocarcinoma with ATP2B1 protein overexpression were higher under different magnifications." (PMID 35875160, 2022). "The expression levels of ATP2B1/4 were compared in cholangiocarcinoma to identify whether the genes were relevant to cholangiocarcinoma progression." (PMID 35875160, 2022). "The results suggest that the modulation of Ca2+ signaling by enhanced ATP2B1 upregulation may transform intrahepatic cholangiocarcinoma from cold tumor to hot tumor and increase the efficacy of immunotherapy." (PMID 35875160, 2022). "Importantly, a cohort of 77 cholangiocarcinoma samples was evaluated by IHC staining to further examinate the relationship between ATP2B1 of expression and patient prognosis." (PMID 35875160, 2022). "In conclusion, we revealed ATP2B1 can be a prognostic factor for cholangiocarcinoma." (PMID 35875160, 2022).
clear cell renal cell carcinoma (1 paper, 2019). "In clear cell renal cell carcinoma (ccRCC), miR-204-3p was found to be down-regulated by the ERβ-suppressed circular RNA ATP2B1, which increased the expression of fibronectin 1 and promoted the invasion of ccRCC cells." (PMID 31850191, 2019).
colitis (1 paper, 2022). Inflammation of the colon. "Western blot analysis of the colon samples confirmed a reduction in plasm membrane Ca2+ pump proteins (PMCA), encoded by Atp2b1, Atp2b2, Atp2b3, and Atp2b4 and recognized by the same antibody, in colitis mice, which was rescued by BBR." (PMID 36528592, 2022).
COVID-19 (1 paper, 2024). A disease caused by infection with severe acute respiratory syndrome coronavirus 2. "Altogether our results link the severity of COVID-19 in patient genomic data (C/C polymorphism in ATP2B1 locus) to our functional in vitro validation results in our genome-edited (C/C) clones." (PMID 38816514, 2024). "As ATP2B1 has been shown to be downregulated in the lungs of COVID-19 patients (Fig. EV1G,H) and here confirmed in our in vitro-infected cellular models, we evaluated if potential genetics associations between ATP2B1 locus and the risk of developing severe COVID-19 occurs." (PMID 38816514, 2024). "Furthermore, a rare homozygous intronic variant of ATP2B1 is shown to be associated with the severity of COVID-19." (PMID 38816514, 2024). "The data presented here underline the marker identification to stratify those people who retain the C/C variant in ATP2B1 (rs111337717), as they might be subjected to severe COVID-19 following virus infection and replication." (PMID 38816514, 2024). "Furthermore, through the search of genetic variants associated with severe disease status we identify a rare (0.038187 global frequency) intronic homozygous polymorphism (“rs111337717”—chr12:89643729, T > C) from the ATP2B1 locus that is positively associated with severity of COVID-19." (PMID 38816514, 2024). "Among these, the expression levels of FOXK2, FOXO3, and FOXP1 were found lower in the lungs of COVID-19 patients, compared to controls, thus showing the same expression levels and trends as observed for ATP2B1 (Fig. EV1G,H)." (PMID 38816514, 2024). "Data from COVID-19 patients show that upon infection the diminishing level of ATP2B1 (Fig. EV1G,H) enhances the pool of intracellular Ca2+ potentially excluding its way-out through the membrane by specific protein pumps." (PMID 38816514, 2024). "Since FOXO3 shows the same expression trend as ATP2B1, with reduced expression levels in the lung of COVID-19 patients (ATP2B1, Fig. EV1G; FOXO3, Fig. EV3E) we hypothesized that FOXO3 is a candidate transcription factor that would be able to control ATP2B1 expression." (PMID 38816514, 2024). "Of interest, we observed decreased levels of ATP2B1 and ATP2B4 in the lungs of COVID-19 patients, while the levels of ATP2A2 were found to increase (Fig. EV1G)." (PMID 38816514, 2024).
Hypocalcemia (1 paper, 2024). An abnormally decreased calcium concentration in the blood. "We describe the first case of biallelic, compound heterozygous ATP2B1 variants in a proband with a neurodevelopmental phenotype, characterized by distinctive craniofacial and skeletal features, and persistent hypocalcemia due to primary hypoparathyroidism." (PMID 37926713, 2024).
intrahepatic cholangiocarcinoma (1 paper, 2024). A carcinoma that arises from the intrahepatic bile duct epithelium in any site of the intrahepatic biliary tree. "It has been recently investigated the correlation between the ATP2B1 gene and the immune microenvironment in intrahepatic cholangiocarcinoma (ICC)." (PMID 38987822, 2024).
neurodevelopmental disability (1 paper, 2023). "In addition to Cdc42, de novo mutations in Atp2b1 are thought to cause a monogenic form of neurodevelopmental disability, according to genetic discoveries, the probands’ overlapping phenotypes, and functional investigations." (PMID 36975497, 2023).
ovarian adenocarcinoma (1 paper, 2022). An adenocarcinoma that arises from the ovary. "Furthermore, ATP2B1 overexpression is associated with cisplatin resistance in human ovarian adenocarcinoma." (PMID 35875160, 2022).
preeclampsia (1 paper, 2020). Preeclampsia is a hypertensive disorder of pregnancy that is characterized by new-onset hypertension with proteinuria presenting after 20 weeks of gestation, and depending on mild or severe forms may initially present with severe headache, visual disturbances, and hyperreflexia. "For instance, we detected a syncytiotrophoblast-specific association between IQ and ATP2B1, a gene that has been implicated in preeclampsia, an in utero condition that is partially mediated by dysfunctional syncytiotrophoblasts and has negative impacts with childhood neurodevelopment." (PMID 33308293, 2020). "In addition, ATP2B1 encodes PMCA1, a plasma membrane calcium ion pump, shown to have reduced activity in fetal-facing syncytiotrophoblast basal plasma membranes in patients with preeclampsia compared to controls." (PMID 33308293, 2020). "Furthermore, we detected a syncytiotrophoblasts-specific association between IQ and ATPase Plasma Membrane Ca2 + Transporting 1 (ATP2B1), a gene whose polymorphic variants have been shown to have associations with preeclampsia." (PMID 33308293, 2020).
prostate carcinoma (1 paper, 2022). A carcinoma that arises from epithelial cells of the prostate gland. "The ATP2B1 contents of extracellular vesicles are increased in prostate cancer treated with enzalutamide and are negatively regulated by androgen receptor." (PMID 35875160, 2022).
viral infection (1 paper, 2024). "Taken together, these data validate the opposite trend observed between viral infection and ATP2B1 expression at the protein level in another cellular model." (PMID 38816514, 2024).
tumor (8 papers, 2020 to 2025). "However, more recently an association between tumor stage and ATP2B1 was identified." (PMID 36009413, 2022). "The tumor tissues with a relatively high ATP2B1 expression contained more immune stromal components and had a higher ESTIMATE score." (PMID 35875160, 2022). "The cohort of PDAC patients was divided into quartiles based on the median-centered ATP2B1–4 tumor expression." (PMID 31963119, 2020). "ATP2B1 was negatively correlated with tumor purity (P=0.004, r=-0.465)." (PMID 35875160, 2022). "ATP2B1 overexpression can activate immune signals and prompt cold tumor response." (PMID 35875160, 2022). "However, the molecular mechanism of ATP2B1 in regulating tumor immune microenvironment needs to be further studied both in vivo and in vitro." (PMID 35875160, 2022). "Consistent expression trends were observed, with ATP2B1.AS1, AP003555.1, and NSMCE1.DT significantly overexpressed in tumor tissues." (PMID 37629096, 2023). "Gene chip microarray data showed that ATP2B4 was predominantly over-expressed (2.65-fold, n = 39, p < 4.06−10) to a much greater extent than ATP2B1 (1.24-fold, n = 39, p < 0.035) in human PDAC tumors versus resected healthy tissue from the tumor margin." (PMID 31963119, 2020).
cancer (7 papers, 2010 to 2025). A tumor composed of atypical neoplastic, often pleomorphic cells that invade other tissues. "They found that the G-allele of PLCE1 rs932764 and the G-allele of ATP2B1 rs17249754 are protective to doxorubicin-induced cardiotoxicity in pediatric cancer survivors." (PMID 36536332, 2022). "Accordingly, the early-stage control of AC025034.1 would also compensate for the ATP2B1 function in cancer cells." (PMID 35031021, 2022).
ATP2B1 also shares sentences with these, for which no sentence is quoted: essential hypertension (8 papers); glioma (2); infection (2); melanoma (2); acute respiratory distress syndrome (1); adenoma (1); atherosclerosis (1); cardioembolic stroke (1); cardiomyopathy (1); cardiovascular disease (1); coronary artery disease (1); Hearing impairment (1); heart failure (1); Hypomagnesemia (1); invasive breast carcinoma (1); ischemic stroke (1); kidney disease (1); large artery stroke (1); liver fibrosis (1); lung carcinoma (1); male infertility (1); muscular dystrophy (1); neurodegenerative disease (1); neurodevelopmental disorder (1); Obesity (1); oral cancer (1); renal fibrosis (1); small vessel stroke (1); thrombosis (1).